CRH (corticotropin releasing hormone)
Diseases named in the same sentence as CRH in open-access papers (continued):
Sharing a sentence is not in itself a finding about the gene and the disease.
depression (continued). "Melancholia and atypical depression are two subtypes of depression with marked differences in clinical expression and in the corticotropin releasing hormone (CRH) system, where the changes in the CRH system are responsible for several of the clinical features." (PMID 28931368, 2017). "Increased plasma corticotropin-releasing hormone and cortisol in depression rats also confirmed that the model had been established." (PMID 28293639, 2017). "A hyperactive hypothalamo–pituitary–adrenal (HPA) axis is often a feature of depression, and activation of the corticotropin-releasing hormone (CRH) neurons in the hypothalamic paraventricular nucleus (PVN) is the central motor for HPA activity." (PMID 28608287, 2017). "This occurred simultaneously with a large effort to target CRH signaling in various stress related disorders (Major Depression, PTSD, addiction)." (PMID 28633663, 2017). "Biochemical tests revealed significantly increased plasma corticotropin-releasing hormone and cortisol in depression rats (P < 0.05)." (PMID 28293639, 2017). "Regarding the DEX/CRH test, it has been reported that 60–80 % of patients with depression exhibited an increased cortisol response prior to the initiation of treatment." (PMID 27582123, 2016). "The current standard method is a DEX/CRH test in combination with the administration of CRH, which has been reported to increase the sensitivity from 60 to 80 % for the classic type of depression." (PMID 27582123, 2016). "In a recent review, scientists concluded that CRH dysfunction is related to depression and anxiety disorders, thus playing an important role in behavioral adaptation and maladaptation in response to stress." (PMID 26334745, 2015). "This gives rise to the failure in the secretion of cortisol and glucocorticoids depending on the type of depression and to the hypersecretion of corticotropin-releasing hormone (CRH)." (PMID 26180581, 2015). "Then, the proinflammatory cytokines activate the CRH of the PVN and upregulate ACTH and cortisol, and abundant of studies suggest that the overexpression of CRH is the key link between the chronic stress and depression." (PMID 24995360, 2014). "With regard to GR, there are several studies in the literature with dexamethasone (alone or in combination with CRH) in depression." (PMID 24478730, 2014). "Looking at 361 studies, the results show that overall depression is associated with small-to-moderate elevations in ACTH and cortisol and a reduction in CRH levels." (PMID 24385966, 2013). "Investigations with depressed patients have shown that the number of CRH neurons increases in the PVN of the hypothalamus of patients with depression, and pituitary volume decreases in patients with bipolar disorder." (PMID 23874274, 2013). "Increased concentrations of CRH were found in the cerebrospinal fluid (CSF) of a subset of patients with depression and also a number of endocrine function tests were in agreement with elevations of central CRH in many severely depressed patients." (PMID 23882180, 2013). "Hypersecretion of central CRH is thought to play an important role in the pathophysiology of stress-related mental disorders, such as major depressive disorder and PTSD." (PMID 23882180, 2013). "Studies have suggested that increased serum levels of CRH, CORT, and ACTH are associated with an increased risk of depression." (PMID 24367385, 2013). "Raised levels of CRH in regional brain and cerebrospinal fluid (CSF) are a consistently replicated finding in patients with depression, and is also seen in suicide victims, rendering CRHR1 an attractive candidate gene for MDD susceptibility." (PMID 23680237, 2013). "Previous studies have shown that increased serum levels of CRH, CORT, and ACTH are associated with an increased risk of depression, suicide, and certain types of aggression." (PMID 24367385, 2013). "Once stressors persist the continuous hyperactivity of CRH neurons can lead to anxiety- and depression-like behavior in animals." (PMID 23882180, 2013).
depression (continued). "The excessive CRH secretion and neurotransmission which is involved in the pathophysiology of depressive disorders has been suggested to extend beyond the hypothalamus and to involve several extrahypothalamic brain regions." (PMID 23986909, 2013). "Similar findings were reported in clinical studies, where the disinhibition of REMS during depression was assigned to a synergism of elevated CRH and cortisol activity." (PMID 21435199, 2011). "Hyperactivity of hypothalamic CRH neurons observed in major depression produces a blunted ACTH response to further CRH challenge, likely reflecting a resultant down-regulation of pituitary CRH receptors." (PMID 19165314, 2009). "Certainly chronic and acute stressors such as the tail suspension test, the forced swim test and others have been used to produce depression-like symptoms in mice and have served to study hyperactivity of hypothalamic CRH neurons." (PMID 19165314, 2009). "Notably, corticotropin-releasing hormone and its mRNA are elevated in the brains of suicide victims with depression." (PMID 40428308, 2025). "On the contrary, CRH infusion to healthy subjects reproduces the hypercortisolism of depression." (PMID 38092990, 2025). "Depression is commonly linked to HPA axis dysregulation, typically presenting with elevated basal cortisol, impaired suppression in the dexamethasone suppression test, and sustained elevation of corticotropin-releasing hormone." (PMID 40428308, 2025). "Notably, adverse psychiatric symptoms, such as those observed in depression, activate the release of hypothalamic CRH." (PMID 38772922, 2024). "Moreover, it has been found that, in chronic stress and depression, the effects of CRH on ACTH release are strongly enhanced by vasopressin, which is produced in increasing amounts when the hypothalamic PVN and SON neurons are chronically activated." (PMID 39000501, 2024). "Moreover, it has been reported that the activation of the HPA during stress seems to be altered in patients with depression and that vasopressin plays a more important role than CRH in the regulation of ACTH release in this group of patients." (PMID 39000501, 2024). "CRH infusion in healthy individuals induces hypercortisolism as in depression but via ACTH." (PMID 38927393, 2024). "For instance, individuals with severe depression often exhibit impaired signaling in the corticosteroid receptor (CR) pathways, leading to the increased production and secretion of corticotropin-releasing hormone (CRH) in various brain regions." (PMID 39329797, 2024). "Studies in humans have found increased expression of CRH in the caudal DR of persons with depression who died by suicide, suggesting that the caudal DR also may play a role in stress-related psychiatric disorders and suicide risk in humans." (PMID 38705984, 2024). "This is confirmed by our detection of increased serum IL-6, TNF-α, CRH, and CORT levels as well as decreased hippocampal BDNF expression in depression-like mice, these results are both caused by depression and in turn can exacerbate depression." (PMID 39494347, 2024). "Moreover, elevated CRH levels have been found in extra hypothalamic brain regions of individuals with depression who died by suicide." (PMID 37190549, 2023). "In addition, high serum levels of IL-1β stimulate the production of pituitary adrenocorticotropic hormone (ACTH), hypothalamic adrenocorticotropic hormone-releasing hormone (CRH), and adrenal steroids, indirectly leading to depression." (PMID 37692303, 2023). "The CRH-HPA system affects health, and a disrupted system can cause a condition such as depression." (PMID 37998661, 2023). "However, overactivation of the HPA axis in patients with depression can lead to excessive release of CRH and CS." (PMID 37932977, 2023). "This suggests that PACAP may be involved in depression in AD by stimulation the central release of CRH, in a similar way as proposed for other mood disorders." (PMID 37226771, 2023).
depression (continued). "Similarly, animal models of depression induced by CORT or restraint stress show high CRH and GR expression in chronically stressful situations." (PMID 37891920, 2023). "Also, corticotropin-releasing hormone acts directly on these circuits and is involved both in the development of depression and dementia." (PMID 37779209, 2023). "A positive correlation between the Cornell score for depression severity in dementia (Alexopoulos, Abrams, Young, & Shamoian, 1988) and the number of CRH-expressing neurons in the PVN has been found earlier (Meynen, Unmehopa, Hofman, Swaab, & Hoogendijk, 2007)." (PMID 37226771, 2023). "Additionally, changes in the HPA axis occurring in people suffering from severe depressive disorders are related to hypersecretion of corticotropin-releasing hormone (CRH)—the hormone also playing the role of a neurotransmitter in the stress reaction." (PMID 36672102, 2023). "Elevation of mid-gestation CRH and accelerated CRH trajectories were both associated with depression and EPDS score at 3-month but not 6-month postpartum." (PMID 35903273, 2022). "The neuropeptide, CRH, was downregulated in the model and in depression." (PMID 34997033, 2022). "CRH and Cort are hyperactive in the peripheral blood of patients with depression." (PMID 36230412, 2022). "HPA axis activation in depression could lead to the release of several endocrine hormones, including corticotropin-releasing hormone (CRH), adrenocorticotropic hormone (ACTH), and glucocorticoid (GC)." (PMID 36312016, 2022). "Thus, the aim of our study was to investigate serum BDNF and CRH levels in vitiligo patients and healthy controls in relation to the observed symptoms of depression and anxiety disorders." (PMID 35508633, 2022). "The most frequently used cutoff values in the listed studies were 10 or higher (for cortisol studies) and 13 or higher (for CRH studies); scores above those values are generally considered to reflect “possible depression” and “probable depression” in PPD studies." (PMID 35903273, 2022). "Some studies suggest that CRH is increased in depression and anxiety disorders." (PMID 35508633, 2022). "In contrast, a modest and imprecise inverse association was observed between PFOS (β = −3.88, 95% CI = −27.33, 19.56), PFHxS (β = −10.23, 95% CI = −41.98, 21.52), Me-PFOSA-AcOH (β = −10.12, 95% CI = −29.15, 8.91), and CRH among women who experienced depression." (PMID 33824413, 2022). "The relationship between PFNA and CRH was stronger among women who experienced stressful life events, depression, food insecurity, and financial strain relative to women who did not experience these stressors but tests for interactive effects were not statistically significant." (PMID 33824413, 2022). "According to Holsboer, in patients with depression, elevated CRH levels lead to hypercortisolism." (PMID 36554152, 2022). "Excessive corticotropin-releasing hormone (CRH) levels in depression lead to inhibition of the hypothalamic-pituitary-gonadal (HPG) axis and increased cortisol levels which further inhibits the action of gonadotropin-releasing hormone (GnRH) neurons, gonadotrophs, and gonads." (PMID 34430141, 2021). "Hyperfunction of the HPA axis has been shown to be associated with CRH hyperactivity, reduced negative feedback ability, and hypersecretion of glucocorticoids in patients with depression." (PMID 34804417, 2021). "Then, immunofluorescence staining showed that Gpr1 was co-located with CRH and GnRH in the hypothalamus, suggesting that Gpr1 may play a role in the relationship between depression and reproduction." (PMID 34207497, 2021). "Additionally, excessive CRH levels in depression lead to inhibition of the hypothalamic-pituitary-gonadal (HPG) axis." (PMID 34430141, 2021). "Additional activation of CRH neurons is observed in depressive disorders, among others." (PMID 34679364, 2021). "Interestingly, stimulation of CRH neurons in the PVN has been shown to be sufficient to generate depression-like behavior." (PMID 34679364, 2021).
depression (continued). "This may be related to high levels of depression and psychogenic stress in vitiligo patients, which can stimulate the secretion of corticotropin-releasing hormone, thus inducing or exacerbating depigmented lesions." (PMID 33093609, 2020). "Moreover, it was proposed that CRH overexpression in the CeA would be a main factor in the origin and development of depression." (PMID 32499732, 2020). "Also, pro-inflammatory cytokines have a profound stimulatory effect on hypothalamic–pituitary axis hormones and corticotropin-releasing hormone, which are pathways that also contribute to the development of depression." (PMID 32010855, 2019). "Two primary CRH receptor subtypes—CRHR1 and CRHR2—have been described in the central nervous system (CNS) according to their neuroanatomical expression patterns; with CRHR1 appearing to play a key role in mediating the CRH-elicited effects in depression and anxiety." (PMID 30719038, 2019). "Some alterations at the cellular level of the hypothalamus, such as perturbation of hypothalamic peptides such as vasopressin, corticotropin-releasing hormone (CRH), as well as regulatory proteins involved in neurotransmitter metabolism, have been found in depression." (PMID 31920518, 2019). "Attenuated HPA axis responses to the combined dexamethasone and corticotropin-releasing hormone (DEX-CRH) challenge has been reported in women on long-term sick leave with job stress-induced depression, a patient group very similar to clinical burnout patients." (PMID 30576285, 2019). "In a rat model of subclinical hypothyroidism-induced depression, resveratrol not only reduced plasma corticosterone levels and depressive behaviors, but also hypothalamic CRH mRNA expression and levels of thyrotropin-releasing hormone (TRH) and thyroid stimulating hormone (TSH)." (PMID 30200269, 2018). "Particularly in the assessment of disturbed regulation of the hypothalamic-pituitary-adrenocortical (HPA) system, dexamethasone/corticotropin-releasing hormone (DEX/CRH) has been extensively investigated with a view towards the differential diagnosis of depression prior to the development of NIRS." (PMID 27582123, 2016). "Thus, the DEX/CRH approach should again be considered a potentially useful biomarker for dividing the subclasses of depression." (PMID 27582123, 2016). "Increased and persistent activation of CRH has also been associated with increased activity of the autonomic nervous system in PTSD victims, particularly in a group of women with a history of sexual abuse in childhood with symptoms of depression and anxiety." (PMID 27602003, 2016). "The HPR group had the highest depression scores and a high mean CRH." (PMID 26334745, 2015). "The weight of available data suggests that the pathologic activation of the stress system in patients with major depression, with activation of the CRH and LC-NE systems, occurs predominantly in patients with melancholic depression, though this point is far from being definitively established." (PMID 25878903, 2015). "Thirdly, elevated serum leptin in depression might in turn further promote corticotropin-releasing hormone (CRH) release, as shown in animals and, hence, contribute to HPA system hyperactivity seen in depression." (PMID 25061971, 2014). "The CRH system plays an important role in neuroendocrine and behavioral responses to stress and is regarded as a central component within the pathogenesis of depression." (PMID 24596569, 2014). "Behavioral effects of CRH resemble the core signs and symptoms of stress, depression, and anxiety." (PMID 24596569, 2014). "In addition, the increased CRH expression in the brain regions related to depression, as an effect of positive feedback of GC and parallel occurrence of depressive symptoms, should be estimated." (PMID 23073785, 2013). "Altered dex/CRH test are seen in major depression as well as in chronic stress conditions." (PMID 24385966, 2013).
depression (continued). "DCNP1 may also play a role in the pathogenesis of depressive disorders because it was shown to enhance corticotropin-releasing hormone expression in the hypothalamic paraventricular nucleus." (PMID 23419067, 2013). "IL-6 may induce production of corticotropin-releasing hormone, resulting in hypercortisolemia, which in turn might contribute to depression." (PMID 21701640, 2011). "These authors also stated that elevated REMS may serve as a premorbid precursor of hypersecreted CRH predicting a clinical condition such as depression." (PMID 21435199, 2011). "Likewise CRH antagonists have demonstrated antidepressant and anxiolytic properties in animal models of depression." (PMID 19165314, 2009). "In addition, in outpatients with clinically remitted major depression, higher cortisol levels in the DEX/CRH test are apparently associated with relapse of major depression." (PMID 19177168, 2009). "In humans, the glucocorticoid sensitivity measured by a Dexamethasone suppression test and the combined Dexamethasone suppression/CRH stimulation (Dex-CRH) test used to evaluate the degree of HPA-axis dysregulation in patients with unipolar depression have been shown to be affected by sex." (PMID 19686591, 2009). "Patients with epilepsy often experience high rates of anxiety and depression due to the chronic stress response, which not only affects neurogenesis and synaptic plasticity in various brain regions but also overstimulates the amygdala, making it more sensitive to stress and promoting CRH production." (PMID 40941042, 2025). "5-HT reduction is implicated in depression, and an SSRI-mediated 5-HT increase may normalize beta-receptor down-regulation, offering, in prolonged stress, adaptive self-regulation against excessive CRH–NE activity." (PMID 38927393, 2024). "According to our hypothesis, an impaired function of CRHR1 would fuel the CRH–NE–CRH circuit, supporting the hyperactivation of the HPA axis with increased secretion of NE and cortisol, the latter especially implicated in metabolic and depressive disorders." (PMID 38927393, 2024). "Furthermore, elevated CRH levels in depression inhibit the HPG axis." (PMID 36984518, 2023). "This may explain why measures of chronic stress, including food insecurity, depression, financial strain, and stressful life events, were not independently associated with CRH in our study." (PMID 33824413, 2022). "CRH or glucocorticoid receptor antagonists, insulin receptor or MR agonists, allopregnanolone, and thyroid axis drugs may be new treatment modalities against depression." (PMID 36430254, 2022). "A diminished GABAergic input to the hypothalamic paraventricular nucleus may contribute to the activation of corticotropin releasing hormone-immunoreactivity neurons in depression, most prominently in major depression, which provides a rationale for prescribing GABAergic agonists for these patients." (PMID 35664493, 2022). "Thus, the CRH–ACTH system seems to be involved in different forms of depression." (PMID 32894324, 2021). "Besides that, the increase in the concentration of CRH was positively correlated to depression." (PMID 32382294, 2020). "Studies have been conducted through dexamethasone/corticotrophin‐releasing hormone (DEX/CRH) test and insulin resistance evaluated by the homeostasis model assessment of insulin resistance (HOMA‐R) to demonstrate that HPA axis dysfunction is associated with insulin in patients with depression." (PMID 32281722, 2020). "Moreover, also clinical studies provided evidence of a CRH hyperactivity in depression and anxiety." (PMID 30890970, 2019). "Mice which lack the GABAAR δ subunit (Gabrd-/- mice) exhibit depression-like behaviors restricted to the postpartum period and deficits in maternal care, a finding which has been attributed to the disinhibition of CRH neurons resulting in elevated corticosterone levels during the peripartum period." (PMID 30906252, 2019).